INS (insulin)
Diseases named in the same sentence as INS in open-access papers (continued):
Sharing a sentence is not in itself a finding about the gene and the disease.
diabetes (continued). "Type 1 diabetes mellitus (T1DM) is an autoimmune disease characterized by the dysfunctional metabolism of carbohydrates, fats, and proteins caused by impaired insulin secretion and insulin resistance." (PMID 38857243, 2024). "In this study, in children diagnosed at a young age, parents took care of insulin administration, the measurement of blood glucose levels, meal preparation, and writing in the diabetes diary." (PMID 38713496, 2024). "Narrowing the focus to cases where FFR was positive but non-hyperemic resultswere negative—a pattern more prevalent in the GFR-H group—both arterialhypertension and insulin-treated diabetes markedly reduced the discrepancy riskfor this cohort." (PMID 39484140, 2024). "At doses of 100 mg/kg and 200 mg/kg, EGCG has the potential to help control diabetes by most effectively improving insulin resistance and beta cell function." (PMID 39770980, 2024). "While hyperglycemia has been associated with an increased risk of fracture, these findings are confounded by a number of variables, including the use of antidiabetic medications, particularly insulin therapy, and presence of diabetes-related complications." (PMID 38887632, 2024). "IR is a decrease in the body's efficiency in promoting glucose uptake and utilization by insulin, which is an important feature of diabetes mellitus." (PMID 39911664, 2024). "Although crude model indicated age, duration of diabetes, SBP, and insulin use were associated with greater odds of attendance at the retina specialist visit, the results were not significant in the adjusted model." (PMID 38877501, 2024). "Short-term treatment showed improvements in glucose metabolism, insulin sensitivity, and diabetes-related biomarkers, although LDL-C levels remained unaffected." (PMID 39684468, 2024). "Diabetes itself, insulin use, and diabetes duration were identified as potential factors influencing the association between Diabetes and cancer." (PMID 38831236, 2024). "Islet or β-cell transplantation is a therapeutical approach to substitute the insulin-producing cells which are abolished in type 1 diabetes mellitus." (PMID 39298538, 2024). "Our study showed that preserved C-peptide secretion was common in Chinese individuals with T1D and was associated with diabetes duration, positive GAD autoantibody, and insulin dosage." (PMID 38405156, 2024). "Cystic fibrosis related diabetes (CFRD) is a type of pancreatogenic diabetes characterized by decreased insulin secretion as well as low body mass index (BMI) explained by both low muscle and low fat mass." (PMID 39530118, 2024). "Overall, nanozymes hold great potential in improving insulin sensitivity and reducing insulin resistance in diabetes." (PMID 38711066, 2024). "Body mass index, glucose, diabetes, alcohol, smoking, cholesterol, triglycerides, high-density lipoprotein, low-density lipoprotein, blood pressure, insulin, and obesity were considered as potential confounders in this study." (PMID 38671284, 2024). "Isorhamnetin, a regulator of the insulin signaling pathway, has been shown to improve diabetes by mitigating insulin resistance." (PMID 38167125, 2024). "Continue investigating Out-of-Pocket Expenses (OoPEs) and rationing of insulin and diabetes supplies, including impacts of the COVID-19 pandemic, for people with type 1 diabetes (T1D)." (PMID 38711747, 2024). "Compared to the older age groups, the younger groups had a higher proportion of males, a shorter diabetes duration, were less often treated with insulin, and had a lower prevalence of hypertension and microvascular complications." (PMID 38828412, 2024). "This investigation has yielded insights into the comparative efficacy, safety, and patient reception of once-weekly GLP-1/GIP agonist treatments and basal insulin in the context of type 2 diabetes mellitus (T2DM)." (PMID 39335457, 2024).
diabetes (continued). "Accordingly, AKS-107 treatment efficiently deleted insulin-specific B cells after a 2-week treatment in addition to preventing diabetes in these mice." (PMID 38515750, 2024). "The insulin signaling pathway is essential for the prevention and management of diabetes, which regulates blood glucose levels by enhancing insulin sensitivity or facilitating insulin release to improve glucose metabolism in insulin-resistant states." (PMID 39596859, 2024). "Although our patient was started on insulin therapy with glargine due to decreased endogenous insulin secretion, the diagnosis of type 2 diabetes mellitus provided her with more treatment options than in the case of SPIDDM." (PMID 39247010, 2024). "An essential aspect of bioengineering S. epidermidis strains to treat diabetes is precise and reliable control of single-chain insulin (SCI) analog production." (PMID 39104585, 2024). "She had hyperglycaemia consistent with post-transplant diabetes mellitus (DM) and was started on insulin." (PMID 38290219, 2024). "Alloxan, a common drug used to induce diabetes, creates a model that resembles type 1 diabetes by moderately destroying the β-cells in the islets of Langerhans, leading to reduced insulin release and subsequent hyperglycemia." (PMID 38606255, 2024). "Future randomized controlled trials should use specific predefined diabetes outcomes, assess for microvascular complications, and include measures of insulin resistance and production to further explore mechanisms." (PMID 39302589, 2024). "Chronic tissue inflammation in the context of diabetes manifests within insulin-responsive tissues, notably including adipose tissue, the liver, skeletal muscle, and pancreatic islets." (PMID 38735956, 2024). "Hypoglycemia is a common feature for many human disease conditions ranging from insulin-induced hypoglycemia of neonates, via diabetes to stroke and neurodegeneration." (PMID 38341839, 2024). "Defining the molecular pathways that allow for increased β-cell proliferation, insulin secretion, and cell survival is imperative in designing therapeutic interventions for individuals with diabetes." (PMID 38392328, 2024). "In contrast to GEDA 2021/2022-Diabetes, there are pronounced differences with regard to education, with a higher proportion of insulin treatment in the group with lower educational level." (PMID 39081466, 2024). "If the endocrine function is no longer sufficient to meet an increased demand for insulin due to decreased insulin sensitivity in target tissues (the liver, adipose tissue, and skeletal muscle), type 2 diabetes mellitus (T2DM) develops." (PMID 38550379, 2024). "When the pancreas does not generate enough insulin or when the body cannot effectively utilize the insulin that is produced, diabetes, which is a dangerous, chronic condition, develops." (PMID 39273732, 2024). "Early identification and appropriate treatment of hyperglycemia in prediabetics is essential, as impairments in pancreatic beta-cell functioning and resistance to insulin are already present before the onset of type 2 diabetes mellitus (T2DM)." (PMID 39022458, 2024). "In a broader view, the inhibition of PTP-1B activity by EC, improving insulin sensitivity, can be positively related to diabetes conditions." (PMID 39769244, 2024). "Regarding diabetes medication categories, patients on insulin only and those on both oral diabetic medications and insulin had higher average predictions than those on oral medications only or no medications." (PMID 39418089, 2024). "Those with diabetes grapple with the inability to regulate blood glucose levels due to diminished insulin production, reduced cellular sensitivity to insulin, or a combination of both." (PMID 38280039, 2024). "Terms such as milk, casein, milk proteins, insulin, and chemistry were related to the nutritional value of camel milk and its potential health benefits, especially in managing conditions such as diabetes." (PMID 39897368, 2024).
diabetes (continued). "It is usually used together with insulin, which is the most commonly used drug for diabetes treatment." (PMID 39434840, 2024). "The main reason for lipid abnormalities in diabetes is reduced insulin sensitivity in adipose tissue and liver." (PMID 39765819, 2024). "Around 72 million individuals with diabetes mellitus worldwide rely on insulin for optimal glycemic control." (PMID 38323079, 2024). "Fetuin-A binds to IR and interferes with the activation of the insulin signaling pathway; therefore, it plays a key role in the pathogenesis of insulin resistance and type 2 diabetes mellitus (T2DM) 14,15." (PMID 38481798, 2024). "Hypoglycemia is considered a limiting factor for optimal management of diabetes in individuals who are on insulin therapy." (PMID 38323079, 2024). "The HGF-Met system is instrumental in hepatic metabolism and enhancing insulin sensitivity in animal diabetes models." (PMID 38654922, 2024). "Natural agents exert protective and therapeutic effects on diabetes mellitus through various cellular mechanisms, suggesting their potential as adjuvant therapy alongside conventional medications, aiding in insulin dose reduction and HbA1c improvement." (PMID 38978922, 2024). "STZ is often used to induce diabetes in experimental animals for diabetic animal models as it specifically destroys B cells in the pancreatic islets and decreases insulin secretion." (PMID 38586318, 2024). "Diabetes mellitus is defined as a group of metabolic diseases characterized by chronic hyperglycemia based on insufficient insulin action." (PMID 39513056, 2024). "There was a significant shift in Caitlyn’s diabetes management when she needed to familiarize herself with insulin administration and monitoring blood glucose." (PMID 38570742, 2024). "Disruptions in β-cell function can lead to insufficient insulin production, a key factor in the development of diabetes mellitus." (PMID 39744011, 2024). "Apart from a markedly lowered HOMA-IR score and increased HOMA-β score, which validate the improvement of diabetes (type 2) and resistance to insulin." (PMID 38926327, 2024). "Diabetes was excluded from these models, due to collinearity with metformin, so the interaction between diabetes, insulin, and metformin, using LME growth models controlling for smoking, was separately investigated." (PMID 38055889, 2024). "The molecular connections between insulin action, diabetes, and Alzheimer’s disease, and potential therapeutic interventions focuses on the regulation of glycogen synthase kinase-3 (GSK-3) and impacts neuronal function." (PMID 39571101, 2024). "During the 1950s and 1960s, insulin was further purified and standardized, and by the 1970s, recombinant DNA technology allowed for the production of human insulin, marking a significant advancement in diabetes care." (PMID 39734941, 2024). "As many patients have poor knowledge about diabetes and insulin treatment, the module was drafted to address these problems." (PMID 38694587, 2024). "GLUT4 is expressed on podocytes, which are considered insulin sensitive and develop insulin resistance in animal models of diabetes, whereas GLUT1 is present in the distal tubuli." (PMID 37955868, 2024). "Metformin is the first-line therapy for diabetes, and it improves insulin sensitivity by activating AMP Dependent Kinase (AMPK)." (PMID 39133724, 2024). "Categorical variables (sex: male, preoperative use of IABP, previous cardiac surgery, COPD requiring medical therapy, diabetes mellitus requiring insulin, hypertension, emergent surgery) are expressed in this table as N (%)." (PMID 38562333, 2024). "In vivo, nerve conduction velocity measurements show a significant decrease early after diabetes induction is reversed by insulin therapy." (PMID 38639646, 2024).
diabetes (continued). "In diabetes rats, GA treatment resulted in a dose-dependent decrease in blood glucose level, as evidenced by lowered AUCglucose, insulin levels, and Homeostasis Model Assessment of Insulin Resistance (HOMA-IR) indices." (PMID 39840111, 2024). "Diabetes mellitus is a chronic disease that is characterized by impaired insulin production and action." (PMID 38300703, 2024). "Patient information: patient aged 35, nulligest, with no family history of breast cancer, followed for 15 years of type 1 diabetes on insulin with total control of her diabetes." (PMID 39220553, 2024). "The significant increase in IGF-1 levels in diabetes treatment suggests the capability of AgNP to enhance insulin secretion." (PMID 39770477, 2024). "Diabetes mellitus (DM) is the precursor of other metabolic disorders categorized by high blood sugar levels due to fault in insulin secretion or function." (PMID 38565861, 2024). "Type 1 diabetes mellitus (DM) is an autoimmune disease characterized by the autoimmune destruction of pancreatic β-cells, necessitating a lifelong dependency on insulin." (PMID 38952386, 2024). "This was a cross-sectional study involving patients with diabetes on insulin (group A), metformin only (group B), and healthy controls (group C)." (PMID 39495998, 2024). "Factors including the duration of diabetes before surgery, the type of operative procedure, the patient's age, and presurgical insulin usage can all impact the likelihood of remission." (PMID 39735002, 2024). "It achieves this by protecting pancreatic beta cells and playing a crucial role in regulating insulin signaling, which is key in diabetes management." (PMID 39449720, 2024). "ADSCs can improve insulin sensitivity and enhance insulin secretion through various pathways, thereby alleviating diabetes and its complications." (PMID 38167106, 2024). "The baseline scores reflect the patients’ ratings of their diabetes medication systems prior to the intervention (e.g. medication system they were on before starting basal insulin titration and using MDC)." (PMID 38812671, 2024). "Diabetes is a chronic disease characterized by the inability of the pancreas to produce the necessary insulin because beta cells are damaged or insufficiently functioning." (PMID 38255417, 2024). "When it came to diabetes management, particularly medications and equipment, metformin was the most frequently mentioned form of medication, while insulin was used by only a few participants." (PMID 38523416, 2024). "In contrast, the group treated with 200 mg/kg of alloxan exhibited a diabetes induction rate of 81% with a statistically significant higher average insulin requirement at 7.58 units/kg/day compared to 150 mg/kg of alloxan." (PMID 39070316, 2024). "In both groups, relevant hypoglycemia was only noted in subjects treated with insulin, even though sulfonylureas were often prescribed in subjects with oral diabetes medication only." (PMID 38331895, 2024). "Evidence from the Diabetes Control and Complications Trial (DCCT) and its Epidemiology of Diabetes Interventions and Complications (EDIC) study underscores the efficacy of intensive insulin therapy in reducing the risk of CVD in T1DM patients." (PMID 38882982, 2024). "Other diabetes medications reported included insulin (41.6%), combination therapy of insulin and other agents (5.7%), sulfonylureas such as Diamicron (1.8%), Glucophage (0.5%), and sodium–glucose cotransporter-2 (SGLT2) inhibitors like Jardiance (0.3%)." (PMID 39664090, 2024). "In recent years, there have been significant advancements in diabetes management technology, particularly in the fields of insulin injection and blood glucose monitoring." (PMID 38571669, 2024). "Diabetes is a metabolic disorder characterized by a chronic hyperglycemic condition resulting from defects in secretion and/or insulin action." (PMID 39055210, 2024).
diabetes (continued). "This modulation can enhance insulin signaling and glucose uptake by cells, thereby improving insulin sensitivity and aiding in diabetes management." (PMID 39092264, 2024). "Diabetes primarily results from insufficient insulin secretion or resistance, and poor long-term blood sugar control can lead to various complications." (PMID 38800475, 2024). "Although the hallmark of type 1 diabetes is the autoimmune destruction of insulin producing β-cells, necessitating exogenous insulin, living with diabetes comes with a high psychological burden." (PMID 39539363, 2024). "The paradoxical role of the insulin signaling pathway in insulin-resistant and hyper-insulinemic subjects brings it to the crossroads of diabetes, obesity, and cancer." (PMID 39692821, 2024). "Diabetes is a chronic disease resulting from insufficient insulin production or that cannot be consumed in the body, which results in a long-term metabolic disorder characterized by hyperglycemia." (PMID 39559676, 2024). "Hypoglycemia is a common complication in patients with diabetes treated with insulin and or oral antihyperglycemic agents." (PMID 39085948, 2024). "The incidence of diabetes is increasing worldwide, necessitating the development of innovative therapies to either compensate for decreased insulin levels or replace dysfunctional β cells." (PMID 39105169, 2024). "Astragaloside IV, a glycoside of cyclobutane-type triterpene obtained from Astragalus membranaceus, has the effect of preventing diabetes by inducing a decrease in blood glucose concentration and an increase in plasma insulin levels." (PMID 38799166, 2024). "Regarding diabetes management, 65 (31%) participants used insulin, 122 (57%) used metformin, and 68 (32%) used sulfonylurea/glinides." (PMID 39351535, 2024). "KEGG analysis identified “MAPK signaling pathway”, “Insulin resistance”, “Cell adhesion molecules”, “Tight junction”, “Maturity onset diabetes of the young”, and “FoxO signaling”, among others." (PMID 38238288, 2024). "Patients with diabetes must know the signs and symptoms of hyperglycemia and hypoglycemia, how to correctly self-administer oral medications and insulin to achieve the best glycemic control." (PMID 39415165, 2024). "Diabetes is a metabolic disorder that is typified by chronic hyperglycemia resulting from defects in insulin secretion and/or insulin utilization." (PMID 38255767, 2024). "Imeglimin, a novel mitochondrial bioenergetic enhancer, represents a promising medication for diabetes with the potential to address both insulin resistance and secretion difficulties." (PMID 39742220, 2024). "It is logical to consider that factors influencing adherence to intensified diabetes treatment protocols play a crucial role in the collaborative efforts of patients and providers to mitigate the effects of puberty on insulin needs and glycemic management." (PMID 38553464, 2024). "Stratification by type of diabetes treatment showed a U-shaped association between BMI and mortality in patients with NIDDM, whereas insulin treatment significantly altered the BMI–mortality relationship in both univariable and multivariable analyses." (PMID 37608126, 2024). "Despite the growing prevalence of diabetes, insulin use remained relatively stable, while the utilization of newer antidiabetics, mainly SGLT2Is and GLP1As, has emerged dynamically." (PMID 38658983, 2024). "Risk factors for severe hypoglycemia in pregnant women are a long duration of diabetes, an HbA1c level ≤ 6.5%, and high doses of daily insulin." (PMID 38397994, 2024). "Under fed conditions, insulin AUC was significantly reduced in the diabetes group compared to the control group (p < 0.05), while blood glucose AUC was significantly higher (p < 0.01)." (PMID 38778421, 2024). "Diabetes mellitus is characterized by elevated blood glucose levels due to defects in insulin secretion and/or action." (PMID 39125375, 2024).